RSPO3 (R-spondin 3)
Diseases named in the same sentence as RSPO3 in open-access papers (continued):
Sharing a sentence is not in itself a finding about the gene and the disease.
non-small cell lung carcinoma (2 papers, 2016 to 2025). A group of at least three distinct histological types of lung cancer, including non-small cell squamous cell carcinoma, adenocarcinoma, and large cell carcinoma. "An in vitro study on non-small cell lung cancer (NSCLC) cells demonstrated that RSPO3 overexpression enhances radiosensitivity by inducing pyroptosis." (PMID 41333132, 2025). "In addition, a group from Janssen reported RSPO2 and RSPO3 translocations in 3.0% of 324 non-small cell lung cancer (NSCLC) samples (197 squamous subtype and 127 adenocarcinoma subtype)." (PMID 27338477, 2016).
ovarian tumor (2 papers, 2017 to 2021). "This antibody also has activity in other epithelial tumor types overexpressing RSPO3, including lung and ovarian tumors which have RSPO3 overexpression driven by an unknown mechanism." (PMID 29127379, 2017).
prostate tumor (2 papers, 2021 to 2023). "Also, RSPO3 has been described as one of the genes being upregulated in prostate tumor stroma compared to healthy stroma." (PMID 34663878, 2021). "On the other hand, we focused on six genes (COL4A5, GLIS3, NPR1, OSR2, PLAGL1 and RSPO3) that were significantly downregulated in human prostate tumors as well as upregulated in DU145-R427 cells, suggesting that these genes might negatively interfere with prostate tumorigenesis." (PMID 38045004, 2023).
Anonychia (1 paper, 2011). Aplasia of the nail. "For example, alterations in RSPO4 activity have been reported to cause anonychia in humans, whereas disruption of Rspo2 or Rspo3 in mice affects development of several different systems (skeletal, respiratory or placenta defects)." (PMID 21297984, 2011).
Arthritis (1 paper, 2022). Inflammation of a joint. "Therefore, our analyses also dictate for previously underexplored gene targets in arthritis, such as Rspo3 (effector molecule of WNT pathway) or Ddit4 (hypoxia-induced, regulator of mTOR1 activity)." (PMID 35879783, 2022). "Functional enrichment further supported that the primed genes are heavily involved in inflammatory response, arthritis-promoting functions (Ccl2, Cxcl5, Sphk1) and, interestingly, Wnt pathway (Bmp2, Rspo3, Cd44) and stem cell differentiation (Sox5, Nrp2, Cdk6)." (PMID 35879783, 2022).
cerebral (1 paper, 2023). "Endothelial knockdown or endothelial conditional knockout of RSPO3 intensified MCAO-induced cerebral ischemic injury." (PMID 37805583, 2023).
Cerebral ischemia (1 paper, 2023). Restriction of arterial blood supply to the brain associated with insufficient oxygenation to support the metabolic requirements of the tissue. "We next examined whether the expression of RSPO3 is changed in mouse brain tissue after cerebral ischemia/reperfusion." (PMID 37805583, 2023).
chronic pancreatitis (1 paper, 2024). A chronic inflammatory process causing damage and fibrosis of the pancreatic parenchyma. "Cluster F2 was characterized by expression of markers implicated with inflammatory processes in fibroblasts, such as CD34 and RSPO3, congruent with this cluster predominantly found in patients with chronic pancreatitis." (PMID 39485038, 2024).
cleft lip (1 paper, 2021). Congenital defect in the upper lip where the maxillary prominence fails to merge with the merged medial nasal prominences. "In addition, human RSPO3 was identified as a candidate gene that contributes to cleft lip/palate and dental anomalies, consistent with its role in skeletal development and in human adipose-derived stem cells." (PMID 33712657, 2021).
Crohn disease (1 paper, 2016). A gastrointestinal disorder characterized by chronic inflammation involving all layers of the intestinal wall, noncaseating granulomas affecting the intestinal wall and regional lymph nodes, and transmural fibrosis. "Furthermore, meta-analysis of genome-wide association studies (GWAS) of inflammatory bowel disease (IBD) identified a SNP within RSPO3 as a Crohn’s disease-specific susceptibility locus (rs9491697, p = 3.79E-10, OR = 1.08)." (PMID 27046199, 2016). "Additionally, meta-analysis of genome-wide association studies linked RSPO3 with Crohn’s disease." (PMID 27046199, 2016). "However, as with the majority of loci identified in GWAS studies, the causal variant underlying this association has not been identified, and it is not known whether a gain- or loss- of function at RSPO3 could be implicated in Crohn’s disease susceptibility." (PMID 27046199, 2016).
cutaneous melanoma (1 paper, 2023). A primary melanoma arising from atypical melanocytes in the skin. "In our study, RSPO1 and RSPO3 were identified as important stroma-to-tumor ligands, each interacting with both the LGR4 and LRP6 receptors in cutaneous melanoma." (PMID 36676129, 2023).
Ecchymosis (1 paper, 2018). A purpuric lesion that is larger than 1 cm in diameter. "Consequently, the ecchymosis observed in the pericardial cavity or tail in seriously affected D. rerio embryos by overexpressing C. semilaevis Rspo3 may result from the downregulation of VEGFa." (PMID 29966290, 2018).
gastric atrophy (1 paper, 2022). "However, in the chronic Hp infection model, KO of Rspo3 did not further diminish chief cell numbers and RSPO3 overexpression did not restore chief cells, suggesting that the loss of chief cells observed in Hp-associated gastric atrophy may be due to alterations outside of RSPO signaling." (PMID 36317629, 2022).
glioma (1 paper, 2022). A benign or malignant brain and spinal cord tumor that arises from glial cells (astrocytes, oligodendrocytes, ependymal cells). "Thus, by generating an artificial gradient of these ligands in the microfluidic device we have demonstrated that both SAA1 and to a lesser extent, RSPO3, can drive glioma tumor cell chemotactic invasion." (PMID 35619544, 2022).
Glucose intolerance (1 paper, 2025). Glucose intolerance (GI) can be defined as dysglycemia that comprises both prediabetes and diabetes. "Suppression of Rspo3 exacerbated glucose intolerance and decreased insulin sensitivity in normal chow-fed iLiRspo3KO mice, with these non-beneficial effects persisting 2 months after tamoxifen administration." (PMID 39854351, 2025).
idiopathic pulmonary fibrosis (1 paper, 2020). Idiopathic pulmonary fibrosis (IPF) is a nonneoplastic pulmonary disease that is characterized by the formation of scar tissue within the lungs in the absence of any known cause. "MMP-7 induction by RSPO3 could be an important mechanism by which RSPO3 promotes lung fibrosis, which deserves further study." (PMID 32160239, 2020).
ischemia (1 paper, 2023). A hypoperfusion of the BLOOD through an organ or tissue caused by a PATHOLOGIC CONSTRICTION or obstruction of its BLOOD VESSELS, or an absence of BLOOD CIRCULATION. "Endothelial RSPO3 overexpression ameliorated cerebral ischemic injury, demonstrating that endothelial cell-derived RSPO3 protects neuronal cells from ischemia/reperfusion injury." (PMID 37805583, 2023).
ischemic stroke (1 paper, 2023). A stroke disorder caused by obstruction of blood flow to the brain, due to thrombotic (local blood clot formation) or embolic (due to a blood clot or other material traveling from another site) event. "Therefore, targeting RSPO3 signaling pathway may have important therapeutic value for the treatment of ischemic stroke and other neuronal ischemia-reperfusion disorders." (PMID 37805583, 2023).
liver disease (1 paper, 2025). "The decrease in RSPO3 mRNA expression with advancing liver disease was confirmed by bulk RNA-seq analysis in additional MASLD cohorts." (PMID 40074890, 2025). "RSPO3 expression decreases with HSC activation and is inversely associated with outcomes in patients with alcohol-associated and metabolic dysfunction-associated steatotic liver disease." (PMID 40074890, 2025). "HSC-selective deletion of Rspo3 phenocopies the effects of HSC depletion on hepatocyte gene expression, zonation, liver size, regeneration and cytochrome P450-mediated detoxification, and exacerbates alcohol-associated and metabolic dysfunction-associated steatotic liver disease." (PMID 40074890, 2025). "The positive effects of HSCs on hepatocyte metabolism, regeneration, MASLD and ALD through RSPO3 suggest that reverting HSCs to quiescence or increasing RSPO3 levels may represent a more potent therapeutic approach for most liver diseases compared with inhibiting or killing activated HSCs." (PMID 40074890, 2025).
lung disease (1 paper, 2019). "Lastly, it is worth noting that macrophages associated with lung disease can manifest high levels of the Wnt pathway agonist, R-spondin-3 (RSPO3)." (PMID 31417574, 2019).
lymph node metastasis (1 paper, 2016). "When lymph node metastasis was analyzed, higher RSPO3 expression was found in cases with lymph node metastasis than in cases without (t = −2.346, P = 0.020)." (PMID 27980454, 2016).
metastatic colorectal cancer (1 paper, 2020). "A phase 1 trial of an anti-RSPO3 antibody in patients with metastatic colorectal cancer was associated with partial responses in some patients, although this was not clearly associated with baseline RSPO3 expression." (PMID 33202731, 2020).
necrotizing enterocolitis (1 paper, 2025). Necrotizing enterocolitis (NEC) is a devastating disease that affects mostly the intestine of premature infants. "RSPO3 showed beneficial effects on necrotizing enterocolitis (NEC) mediated by the downstream regulation of adenosine 5’-monophosphate-activated protein kinase α (AMPKα)." (PMID 41333132, 2025).
polyp (1 paper, 2024). A usually exophytic mass attached to the underlying tissue by a broad base or a thin stalk. "DKK1 and DKKL1 showed a significant upregulation in polyp specimens, while WNT10B, GREM1, RSPO3, SFRP5, and GPC3 showed a downward trend." (PMID 38473810, 2024).
renal hypoplasia (1 paper, 2023). Renal hypoplasia is a developmental anomaly in which one or both kidneys (unilateral or bilateral renal hypoplasia, respectively) have a deficit in the number of nephrons and may be small. "Kidney-specific deletion of Rspo3 results in a mild reduction of renal progenitor cells, whereas joint deletion of Rspo1 and Rspo3 resulted in severe renal hypoplasia." (PMID 37580336, 2023).
squamous cell carcinoma (1 paper, 2016). A carcinoma arising from squamous epithelial cells. "The original data from TCGA verified that ADAMTS8, DMBT1 and DOCK8 were down-regulated in adenocarcinoma and squamous cell carcinoma, whereas RSPO3 was overexpressed in adenocarcinoma and down-regulated in squamous cell carcinoma." (PMID 27980454, 2016). "RSPO3 was overexpressed in adenocarcinoma but not squamous cell carcinoma (P = 0.023)." (PMID 27980454, 2016). "We found that RSPO3, ADAMTS8, DMBT1 and DOCK8 were all downregulated in squamous cell carcinoma tissues compared to non-cancerous lung tissues, whereas STMN2, TUSC3 and C8orf22 were upregulated in squamous cell carcinoma (all P < 0.001)." (PMID 27980454, 2016).
type 2 diabetes (1 paper, 2024). "We found that the locus approximately 250 kb upstream and downstream of the gene RSPO3 (hg19, chr6: 127189749–127689749) possessed many significant SNPs associated with type 2 diabetes and fracture, with the nearest gene RSPO3." (PMID 38591545, 2024). "The MR analyses indicated that increased circulating RSPO3 was strongly associated with increased risk of type 2 diabetes (OR = 1.24, 95%CI = 1.16–1.34, p=7.86 × 10−9), but reduced fracture risk (OR = 0.73, 95%CI = 0.66–0.81, p=4.1 × 10−10)." (PMID 38591545, 2024). "We found that higher expression of RSPO3 in adipose subcutaneous would be associated with increased risk of type 2 diabetes, but decreased risk of fracture." (PMID 38591545, 2024). "The conjunctional false discovery rate (conjFDR) analysis identified 10 genomic loci shared between type 2 diabetes and fracture, with the top SNP rs4580892 in the intron of gene RSPO3 (conjFDR = 1.45E-05)." (PMID 38591545, 2024). "Furthermore, after merging the eQTL summary data of RSPO3 in adipose subcutaneous with the summary data of type 2 diabetes and fracture, rs72959041 and rs1936806 were the top cis-eQTL for type 2 diabetes and fracture in GTEx database, respectively." (PMID 38591545, 2024).
ulcers (1 paper, 2022). "Human ulcers show high stromal expression of RSPO3 in the ulcer bed and active YAP signaling in adjacent epithelial cells." (PMID 36099044, 2022). "ISH for RSPO3 revealed a strong expression of RSPO3 in stromal cells in the ulcer bed." (PMID 36099044, 2022). "To this end, we analyzed the spatial expression pattern of RSPO3 and active YAP protein in human ulcer samples." (PMID 36099044, 2022). "In addition, in human ulcers, which typically coincide with H. pylori infection, positive staining for CD44v9 was also detected at the ulcer margin together with strong RSPO3 expression, but was absent from the epithelium more distant from the ulcer site." (PMID 36099044, 2022).
Varicose veins (1 paper, 2023). Enlarged and tortuous veins. "In contrast, genetically increased level of RSPO3 was causally associated with a reduced risk of both varicose veins and certain fractures." (PMID 37404740, 2023). "A recent GWAS identified RSPO3 as a risk locus for varicose veins, which was in consistent with our finding." (PMID 37404740, 2023). "The COLEC11, IRF3, LUM, POSTN, RSPO3, and SARS2 were considered to share the same variant of varicose veins." (PMID 37404740, 2023). "As a result, eight proteins were found to be causally associated with varicose veins, including COLEC11, IRF3, LUM, POSTN, RPN1, RSPO3, SARS2, and VAT1." (PMID 37404740, 2023). "The colocalization analysis indicated that COLEC11, IRF3, LUM, POSTN, RSPO3, and SARS2 shared the same causal variant with varicose veins." (PMID 37404740, 2023). "We identified eight plasma proteins that are significantly associated with the risk of varicose veins after Bonferroni correction (P < 2.495 × 10−5), with five being protective (LUM, POSTN, RPN1, RSPO3, and VAT1) and three harmful (COLEC11, IRF3, and SARS2)." (PMID 37404740, 2023). "However, none of the other identified pleiotropy could completely explain the association with varicose veins, including RPN1, RSPO3, and VAT1." (PMID 37404740, 2023). "Five of eight proteins in primary analysis were finally identified as potential drug targets for varicose veins, including IRF3, LUM, POSTN, RSPO3, and SARS2." (PMID 37404740, 2023). "A comprehensive analysis indicated that IRF3, LUM, POSTN, RSPO3, and SARS2 might be potential drug targets for varicose veins." (PMID 37404740, 2023).
tumor (65 papers, 2015 to 2025). "Blocking RSPO3-mediated Wnt signaling using anti-RSPO3 antibodies disrupts the self-renewal capacity of tumor stem cells, leading to loss of tumor stem cell function." (PMID 41346579, 2025). "PTPRK is a recurrent gene fusion with RSPO3, a Wnt pathway potentiator, particularly in serrated adenoma, a tumour type associated with a more mesenchymal phenotype." (PMID 38904097, 2024). "Lamina propria, SOX6, inflammation and tumor-associated fibroblasts were upregulated, while RSPO3 + fibroblasts were downregulated, and myofibroblasts maintained the same level as control samples." (PMID 38297356, 2024). "Using in vitro experiments as well as a validated ex ovo assay, we show that RSPO3 loss translates into greater invasiveness and extravasation by tumour cells." (PMID 30987640, 2019). "In these latter types of tumors that represent over 90% of CRC, RSPO3 is produced by stromal cells in the tumor microenvironment and the activating mutations appear to sensitize the tumors to Wnt-Rspo synergy." (PMID 29127379, 2017). "In the OMP-C8 PDX model, an APC mutated tumor, three cycles of anti-Rspo3 + nab-paclitaxel treatment dramatically reduced the cancer stem cell frequency by 40-fold, as assayed by the limiting dilution assay (LDA)." (PMID 29127379, 2017). "To achieve this goal, we investigated Runx1 and Foxp3 participation in the regulation of expression of two tumor associated genes, Rspo3 and GJA1, which are known modulators of breast tumor cell growth (positively and negatively, respectively)." (PMID 26735887, 2016). "Dysregulatin on RSPO3 (a R‐spondins ligand of LGR4)‐LGR4 signaling in LUAD with Keap1 deficiency could facilitate tumor aggressiveness." (PMID 40364562, 2025). "Similarly, RSPO3, which encodes for a secreted signaling molecule and potentiates Wnt/β-catenin signaling, is characterized as a tumor promoter." (PMID 38045004, 2023). "More selective approaches may offer a viable alternative, as shown recently by blockade of RSPO3, which inhibited tumor growth of PTPRK-RSPO3 fusion-expressing CRC by promoting differentiation and loss of stem-cell function." (PMID 30664649, 2019). "Activation of β‐catenin is instrumental in GC spheroid formation and tumor‐initiating capacity, and previous reports have demonstrated that RSPO3 potentiates the Wnt/β‐catenin signaling pathway." (PMID 38581123, 2024). "In contrast, the number of tumor lesions was significantly reduced in Rspo3 overexpressing mice compared to control compared mice." (PMID 37932819, 2023). "Our results demonstrated that targeted methylation of RSPO3 significantly increased TFK1 tumor volume, which also resulted in accelerated tumor growth and increased weight." (PMID 37932819, 2023). "In this regard, targeted demethylation of RSPO3 significantly reduced QBC939 tumor volume, which was also evident in slower tumor growth and lower tumor weight." (PMID 37932819, 2023). "The ratio of liver weight to body weight in mice showed a significant decreased tumor load with Rspo3 overexpression." (PMID 37932819, 2023). "Hematoxylin and eosin (H&E) staining showed a significant increase in the number of tumor lesions in Rspo3 knockdown mice compared to control mice." (PMID 37932819, 2023). "SCRN1 accelerates tumor progression by the regulation of exocytosis of matrix metalloproteinase-2/9 (MMP-2/9), while RSPO3 is an oncogenic driver that causes CRC and extensive crypt hyperplasia, concomitantly stimulating stem cells and supportive niche cells." (PMID 37228491, 2023). "N-cadherin reflects the infiltration ability of tumor cells, and immunohistochemical staining by N-cadherin showed that the degree of tumor infiltration increased in tumors targeting RSPO3-methylated TFK1." (PMID 37932819, 2023). "The ratio of liver weight to body weight in mice showed a significant increase in Rspo3 knockdown tumor load." (PMID 37932819, 2023).